VCAM1 (vascular cell adhesion molecule 1)
Diseases named in the same sentence as VCAM1 in open-access papers (continued):
Sharing a sentence is not in itself a finding about the gene and the disease.
cancer (continued). "Apigenin is able to reduce cancer cell glucose uptake, inhibit remodeling of the extracellular matrix, inhibit cell adhesion molecules that participate in cancer progression (like VCAM-1), and oppose chemokine signaling pathways that direct the course of metastasis into other locations." (PMID 27355071, 2014). "These interactions could involve endothelial adhesion molecules such as ICAM-1, VCAM-1 and E-selectin which have been shown to play an important role for the interactions between cancer cells and the endothelium monolayer." (PMID 24857933, 2014). "The interaction between ICAM-1/VCAM-1 and their respective ligand may facilitate the adhesion of cancer cells to the vascular endothelium, and subsequently aid in the promotion of metastasis." (PMID 24555415, 2014). "We found that cell detachment increased cellular hydrogen peroxide and hydroxyl radical generation and such reactive oxygen species (ROS) were responsible for the increasing interaction between cancer cells and endothelial cells through vascular endothelial cell adhesion molecule-1 (VCAM-1)." (PMID 23460862, 2013). "Since the interaction of ITGA4 with VCAM-1 is essential for the leukocyte adhesion cascade involving rolling, adhesion and transmigration through endothelial cells, DcR3 might enable cancer cells to mimicry this process in order to form distant metastasis." (PMID 24107265, 2013). "β1 integrins also participate in cancer cell attachment to mesothelial monolayers, which could reflect that cancer cells are binding to the mesothelium-associated ECM and/or to mesothelial cell surface VCAM-1." (PMID 22527451, 2012). "In addition to causing mesothelial retraction, TNFα and other inflammatory mediators upregulate ICAM-1 and VCAM-1 adhesion molecules on mesothelial cells, which facilitates cancer–mesothelial cell interactions." (PMID 22527451, 2012). "This study examines for the first time the serum concentrations of circulating VCAM-1 and E-selectin in a consecutive series of 110 cancer patients seen in a general medical oncology clinic, and confirms and extends previous studies reporting measurement of circulating ICAM-1." (PMID 7686390, 1993). "Moreover, activation of EGFR signaling has been shown to elevate Vcam1 levels in cancer cells." (PMID 40683857, 2025). "The authors showed that MAMs, mainly originated from circulating inflammatory monocytes (IMs), could interact with metastatic cells and activation of the CCL3–CCR1 axis promotes adhesion of macrophages to VCAM-1 (Vascular cell adhesion protein 1) expressing cancer cells through integrin α4." (PMID 38037106, 2023). "Under situations of chronic diseases and high levels of inflammation, VCAM-1 is also expressed on the surface of other cells, including tissue macrophages, dendritic cells, bone marrow fibroblasts, myoblasts, oocytes, Kupffer cells, Sertoli cells, and cancer cells." (PMID 36880057, 2023). "This work combines the VCAM-1 inhibitor Suc and the chemotherapeutic Dox in a well-designed nano-delivery system to suppress primary tumors and their lung metastases simultaneously, which provides a promising drug delivery strategy for the treatment of metastatic malignant tumors." (PMID 36839671, 2023). "Moreover, cancer cells may shift their behavior more towards growth by their expression of VCAM1 and the release of signals related to the NFkB pathway." (PMID 36900309, 2023). "Cancer-associated fibroblasts (CAFs), the predominant stromal cells of TME, modulate tumor progression by secreting various pro-inflammatory cytokines (IL-6, IL-8, TGF-β, hepatocyte growth factor (HGF), vascular cell adhesion molecules-1 (VCAM-1), and chemokines (CXCL12, CXCL14, CXCL1)." (PMID 35927239, 2022). "Together, these studies suggest that VCAM-1 might be a potential target for cancer immunotherapy." (PMID 35832090, 2022).
cancer (continued). "Some of the significant cancer hallmark terms are inflammatory response (CD14, CD69, IL10RA), KRAS signaling up (CD37, IL10RA, GPNMB), IL-6/JAK/STAT3 signaling (CD14, CSF2RB), Interferon Gamma Response (CD69, CSF2RB, IL10RA, VCAM1, SLAMF7), TNF-alpha Signaling via NF-kB (CD69)." (PMID 35486660, 2022). "Under high levels of inflammation and chronic conditions in some diseases, VCAM-1 also is expressed on the surface of other cells, including tissue macrophages, dendritic cells, bone marrow fibroblasts, myoblasts, oocytes, Kupffer cells, Sertoli cells, and cancer cells." (PMID 29614819, 2018). "More interestingly, our cell–cell binding assays demonstrated that aberrant expression of VCAM-1 on PDAC cells might tethers monocytes to cancer cells through counter–receptor interactions, providing a survival advantage to PDAC cells that infiltrate leukocyte-rich microenvironments." (PMID 29670110, 2018). "Thus, we concluded that VCAM-1 on PDAC cells might tether monocytes to cancer cells via counter–receptor interaction, providing a survival advantage to PDAC cells that infiltrate leukocyte-rich microenvironments." (PMID 29670110, 2018). "Hence, ICAM-1 and VCAM-1 in both cancer and endothelial cells may play synergistic roles in metastasis progressions." (PMID 26690142, 2015). "Thus, the issue of whether the resistin-initiated endothelial adhesion of CRC cells through ICAM-1 and VCAM-1 in CRC cells is controlled by cancer cell-leukocyte interactions warrants further investigation." (PMID 26690142, 2015). "Since VCAM-1 is involved in inflammatory reaction and systemic inflammatory response in cancer patients is a common phenomenon, there is a need to elucidate whether detected concentrations of sVCAM-1 in serum are truly cancer-specific." (PMID 25177246, 2014). "However, there is no detailed information about whether resistin induces ICAM-1 and VCAM-1 expressions in cancer cells, and hence promotes its adhesion and invasion of the endothelium." (PMID 24555415, 2014). "In order to explain these apparently contrasting results, we hypothesize that in the first 6 hours, the exosomes treatment of HUVECs induces the expression of VCAM1 to allow the adhesion of the cancer cells on the endothelium, as the first step of cells migration." (PMID 25015105, 2014). "Since VCAM-1 is an endothelial ligand for interacting with β1 sub family of integrins, we hypothesized that hydrogen peroxide and hydroxyl radical probably affected the expression level and/or function of integrins on cancer cell surfaces." (PMID 23460862, 2013). "The anti-VCAM-1 treatment may be a new potential therapeutic strategy for malignant tumors." (PMID 23593320, 2013). "In this study, VCAM-1 levels were significantly upregulated in the GC tissues, consistent with a previous report on VCAM-1 overexpression in various cancer types." (PMID 40927361, 2025). "This systematic review indicates that regular exercise is associated with only small and statistically nonsignificant changes in circulating angiogenesis biomarkers, including VEGF, VCAM-1, and MCP-1, in patients with cancer." (PMID 41583457, 2025). "VCAM‐1 expression was previously shown to be upregulated on mesothelial cells by TNF treatment, thereby enabling cancer‐mesothelial cell interactions leading to OC cell attachment and invasion." (PMID 38566518, 2024). "Similar to these findings, others have also shown WISP1-mediated upregulation of VCAM1 and ICAM1 are crucial for cancer cell migration, invasion, and wound healing." (PMID 39682753, 2024). "Vascular cell adhesion molecule-1 (VCAM1) is expressed by endothelial cells, immune cells, and cancer cells." (PMID 38332012, 2024). "Finally, the molecular expression of specific genes that are involved in dormancy control might be common to different types of cancer, such as Axl, which encodes for the tyrosine-protein kinase receptor UFO (an enzyme of the TAM family) and vascular cell adhesion molecule 1 (VCAM-1)." (PMID 36902406, 2023).
cancer (continued). "Key events in this process are mediated by IL-1β and IL-18 signaling, as both cytokines accelerate the expression of vascular cell adhesion molecule 1 (VCAM1) in hepatic sinusoidal endothelial cells (HSECs), assisting the adhesion of cancer cells." (PMID 37891577, 2023). "Thus, designing a nano-system to co-deliver the VCAM-1 inhibitor Suc and the chemotherapeutic Dox might simultaneously eliminate primary tumors and their metastases, which will be greatly beneficial for the treatment of metastatic malignant tumors." (PMID 36839671, 2023). "BC cell conditioned medium, or cancer cells in transwell co-cultures up-regulate the adhesion molecules ICAM-1 and VCAM-1 and decrease migration and MT1-MMP and MMP-2 expression in endothelial cells." (PMID 35884405, 2022). "A study also found adipocytes in bone marrow promoted bone proliferation, tropism, and cancer cell survival by secreting factors such as TNF-α, vascular cell adhesion molecule 1 (VCAM-1), adiponectin, IL-1B, and IL-6." (PMID 36675715, 2022). "We found that cotransfection with siPTEN and siOTUD1 attenuated the increase in phosphorylated AKT, VCAM1 and CXCL8 and cancer cell proliferation induced by knockdown of OTUD1 alone." (PMID 35280681, 2022). "These cytokines have been identified to be directly or indirectly responsible for cancer progression through remodeling of ECM by upregulating the expression of molecules such as MMP2, MMP3, MMP9, MMP10, MMP13, PLAU, ICAM1 and VCAM1." (PMID 34946170, 2021). "Cancer cells promote neutrophil ET formation and are closely related to the inflammatory cytokines ICAM-1, VCAM-1, E-selectin, IL1, IL6, CXCL1, and C3a receptors." (PMID 34084158, 2021). "Cancer cell intravasation/extravasation is also largely influenced by PFKFB3, as it increases the expression of tumor cell adhesion molecules, VCAM-1, ICAM-1, and E- selectin by NF-κB signaling." (PMID 34831136, 2021). "This last group included genes involved in cell migration and ECM (e.g. RAB6B, FN1, VCAM1 or COL14A1) and genes of signalling pathways usually deregulated in cancer, such as Notch and Wnt signalling (JAG1 and WNT7B, respectively)." (PMID 34353313, 2021). "Next, we used cBioPortal to evaluate the correlations between the levels of FGL2 and the cancer-promoting cytokines measured above (IL-10, MMP9, CCL5, TIM-3, IL-13, VCAM1, M-CSF and FGF-7) in ESCA tissues." (PMID 33323552, 2020). "Several inflammatory cytokines, such as CD31, BDNF, TFF3, Serpin E-1, VCAM-1, Vitamin D BP, and PDGF-AA, were significantly upregulated in cancer survivors while MMP9 and Osteopontin both had significant positive correlations with barriers to care." (PMID 32587352, 2020). "For example, several cancer cells’ surface-expressed integrins (such as αvβ3, β5 integrins), ligand sialyl Lewis (sLex), and endothelial receptors (ICAM-1,VCAM-1) reportedly contribute to the adhesion of cancer cells to endothelia." (PMID 33379338, 2020). "In the first week after cancer cell inoculation, marked glycocalyx disruption (SDC-1 and ESM-1) and notable activation of pro-inflammatory adhesion molecules [soluble VCAM-1 (sVCAM-1)] were detected." (PMID 30683749, 2019). "BMA secrete various adipocytokines such as leptin, adiponectin, IL-1β, IL-6, vascular cell adhesion molecule 1 (VCAM-1), TNF-α, and VEGF, which influence cancer cell biology." (PMID 31334678, 2019). "High VCAM-1 expression and CD206 (+) macrophages infiltration were observed in cancer tissues compared with normal tissue in CRC, these findings were further analyzed by flow cytometry." (PMID 30894509, 2019). "IL-1β and TNFα induced IL-18 release upregulating the expression of VCAM-1 on hepatic sinusoidal endothelium (HSE) and thereby promoting cancer cell adhesion and liver metastases." (PMID 30042333, 2018). "Integrins such as vascular cell adhesion molecule 1 (VCAM-1) and intercellular adhesion molecule 1 (ICAM-1) have been shown to be involved in metastasis and cancer cell migration." (PMID 30105032, 2018).
cancer (continued). "Increased permeability of the pulmonary endothelium in the 3rd week after cancer cell inoculation correlated with a transient increase in VEGFA and VCAM-1 expression in the lungs." (PMID 30075800, 2018). "This review covers the role and relevance of VCAM-1 in inflammation, and also highlights the emerging potential of VCAM-1 as a novel therapeutic target in immunological disorders and cancer." (PMID 29614819, 2018). "One earlier report indicates that the interaction between VCAM-1 and CD44 on a cancer cell's surface can induce ABCG2 expression." (PMID 28969049, 2017). "Subsequently, we performed FACS detection of CAMs, and the results showed that cancer group cells had increased CD18 (ITGB2), CD106 (VCAM-1), and CD31 (PECAM-1), with decreased CD54 (ICAM-1)." (PMID 28350008, 2017). "Our data showed that the interaction of cancer and endothelial cells increases COX-2, IL-8, ICAM1 and VCAM1 mRNA levels of HUVECs." (PMID 28173828, 2017). "Because cell adhesion molecules have been shown to be critical in cancer cell metastasis, we examined the effect of resistin on the ICAM-1 and VCAM-1 mRNA and cell surface protein expressions in SK-Hep1 cells." (PMID 24555415, 2014). "Activation of endothelial cells by IL-1β induced the expression of ECAMs namely VCAM-1, ICAM-1 and E-selectin on endothelial cell surfaces, and these proteins facilitated the binding of cancer cells." (PMID 23460862, 2013). "Cell adhesion molecules (CAMs), such as vascular endothelial cell adhesion molecule-1 (VCAM-1), intercellular cell adhesion molecule-1 (ICAM-1), and E-selectin, have been shown to be essential for endothelial cells in interaction with the cancer cells." (PMID 23460862, 2013). "In our analysis, cancer incidence in PWH was related to increased levels of PCT and VCAM-1." (PMID 40006998, 2025). "Although predominantly expressed by endothelial cells, during acute inflammation or chronic conditions in some diseases, VCAM-1 can be expressed by non-endothelial cells (e.g., cancer cells, macrophages, DCs)." (PMID 39596815, 2024). "Notably, TBMS1-treated VECs expressed lower levels of the adhesion molecules VCAM-1 and ICAM-1, which were involved in cancer cell intra/extravasation." (PMID 38230220, 2024). "Critically, VCAM-1 upregulation increased the proliferation and migration of cancer cells, and also mediated the recruitment of TAMs to the PDAC TME, facilitating the binding of TAMs to cancer cells." (PMID 38339310, 2024). "The cancer-induced increase of integrin expression in EC as well as the reciprocal expression of the integrin ligands, VCAM-1 and ICAM-1, on the surface of the cancer cells is the opposite to what is described for the interactions between EC and ALL cells as well as EC and normal lymphocytes." (PMID 37173970, 2023). "We found the expression of direct interaction partners in cancer cells and LEC, such as Itga4 and Vcam1, which could modulate heterotypic adhesion and maintenance at not only the same niche but also vessel remodeling and immune recruitment." (PMID 37686421, 2023). "Moreover, the integrin α4β1, which is expressed by cancer cells, can serve as an alternative ligand for vascular cellular adhesion molecule 1 (VCAM-1 or CD106) to mediate the firm adhesion of cancer cells to the endothelium." (PMID 37215087, 2023). "In the process of extravasation, adhesive molecules, such as E-selectin, vascular cell adhesion molecule 1 (VCAM-1), intercellular adhesion molecule 1 (ICAM-1), or very late antigen-4 (VLA-4), are expressed to ensure interactions between cancer cells and the BBB." (PMID 35884446, 2022). "Interestingly, 7 of the top 10 oncogene candidate protein-coding genes identified (e.g., FSTL1, VCAM1, VWF) were shown in other cancer types to promote cell migration, invasion, or metastasis." (PMID 36359790, 2022).
cancer (continued). "We also showed that PTEN ablation could attenuate the decrease in phosphorylated AKT, VCAM1 and CXCL8 and cancer cell proliferation mediated by overexpression of OTUD1 in 786-O cells." (PMID 35280681, 2022). "Additionally, the contact bone marrow MSC-leukemic cell-VLA-4 and VCAM-I mediated increases factors contributing to cancer cell survival like IL-8, IL-6, VCAM-1, and CCL2, known to correlate with high infiltration of macrophages promoting cancer cell growth." (PMID 34680425, 2021). "Moreover, previous studies have shown that downregulation of VCAM1, ICAM1, and CDH2 can inhibit cancer cell proliferation and migration." (PMID 34098960, 2021). "We note that the increase is not dramatic, and preliminary experiments using antibodies to block VCAM-1 or P-selectin failed to dampen the ability of CTX to increase cancer cell arrest." (PMID 34638621, 2021). "Moreover, some antibodies target only specific cancer types (e.g., PSMA-, HER2-expressing tumors) or lack cancer-specificity because their targets are expressed also by other cells (e.g., CD133, VCAM-1, ICAM-1)." (PMID 32260071, 2020). "While vascular cell adhesion molecule-1 (VCAM-1), a cell adhesion molecule, is known to be expressed on endothelial cells in an inflammatory condition and helps adhesion of immune cells, it has been suggested to have an important role in cancer biology." (PMID 33273652, 2020). "Expression of VCAM-1 and ICAM-1 seems to be closely related to the metastasis of cancer cells." (PMID 33103723, 2020). "Furthermore, VCAM1 significantly influenced the invasion and metastasis of CRC cells in vitro and in vivo and activated the EMT program, by which cancer cells adhere to the endothelium and cross the vessel wall by forming pseudopodia and invadopodia." (PMID 32793471, 2020). "Human endothelial cells stimulated with microparticles obtained from cancer patients post-VEGFi treatment induced a significant increase in gene expression of pro-inflammatory markers including TNF-α, IL-6, MCP-1, iNOS, COX-2, and VCAM-1." (PMID 30753341, 2019). "Endothelial selectins, such as: P-selectin, E-selectin, and the intercellular adhesion molecules: Intercellular Adhesion Molecule 1 (ICAM-1), Vascular cell adhesion molecule 1 (VCAM-1) and their ligands, have been related to immune cell and cancer cell adhesion to the vasculature." (PMID 31382462, 2019). "Previous studies showed that MCPIP3 inhibits the expression of proinflammatory genes, such as vascular cell adhesion molecule (VCAM)-1, in human endothelial cells, but the roles and functions of MCPIP3 in cancer cells are still unknown." (PMID 29751537, 2018). "Concurrently, protein expression levels of VCAM-1, ICAM-1, resistin, biomarkers in plasmas are clearly up regulated during initial stage of cancer, but significantly down regulated in later stages of cancer in patients." (PMID 29606130, 2018). "While unexposed monocytes have low expression of PDL1, CD163, and CD206 (black solid lines), exposure to mf, similar to those of cancer cell lines, significantly upregulate the cell surface expression of PDL1 (inhibitory), PDL2 (M2/inhibitory), CD206 (M2), and VCAM-1(M1)." (PMID 29668679, 2018). "Bone marrow adipocytes also secrete several pro-inflammatory mediators such as IL-1B, IL-6, leptin, adiponectin, vascular cell adhesion molecule 1 (VCAM-1), tumor necrosis factor alpha (TNF-alpha) and CXCL12 that increase bone tropism, proliferation, and survival of certain cancer cells." (PMID 28800754, 2017). "Adhesion molecules, such as intracellular adhesion molecule-1 (ICAM-1), vascular cell adhesion molecule-1 (VCAM-1), E-cadherin and E-selectin plays a central role in endothelial adhesion of a number of cancer cells and are closely related to cancer invasion and metastasis." (PMID 27834913, 2016). "In addition to its role in cancer cells, we found that blockade of Hh signaling led to decreased production of stromal cell secreted factors (SDF-1, IL-6 and VCAM-1)." (PMID 26885608, 2016).